NTRK1 (neurotrophic receptor tyrosine kinase 1)
Description:
Receptor tyrosine kinase involved in the development and the maturation of the central and peripheral nervous systems through regulation of proliferation, differentiation and survival of sympathetic and nervous neurons. High affinity receptor for NGF which is its primary ligand. Can also bind and be activated by NTF3/neurotrophin-3. However, NTF3 only supports axonal extension through NTRK1 but has no effect on neuron survival (By similarity). Upon dimeric NGF ligand-binding, undergoes homodimerization, autophosphorylation and activation. Recruits, phosphorylates and/or activates several downstream effectors including SHC1, FRS2, SH2B1, SH2B2 and PLCG1 that regulate distinct overlapping signaling cascades driving cell survival and differentiation. Through SHC1 and FRS2 activates a GRB2-Ras-MAPK cascade that regulates cell differentiation and survival. Through PLCG1 controls NF-Kappa-B activation and the transcription of genes involved in cell survival. Through SHC1 and SH2B1 controls a Ras-PI3 kinase-AKT1 signaling cascade that is also regulating survival. In absence of ligand and activation, may promote cell death, making the survival of neurons dependent on trophic factors. [Isoform TrkA-III]: Resistant to NGF, it constitutively activates AKT1 and NF-kappa-B and is unable to activate the Ras-MAPK signaling cascade. Antagonizes the anti-proliferative NGF-NTRK1 signaling that promotes neuronal precursors differentiation. Isoform TrkA-III promotes angiogenesis and has oncogenic activity when overexpressed.
Synonyms: Trk-A; MTC; TRK; TRKA; TRK1; p140-TrkA
Tractability: Small molecule: an approved drug acts on it; a structure with a bound ligand is known; a high-quality ligand is known; it has a high-quality binding pocket; it belongs to a druggable protein family. Antibody: UniProt places it where antibodies can reach, with high confidence; its Gene Ontology location is reachable by antibodies, with high confidence; UniProt predicts a signal peptide or a membrane-spanning region. PROTAC: it is named in the literature on targeted protein degradation; UniProt records ubiquitination sites on it; a small molecule that binds it is known. Other modalities: an approved drug acts on it.
Target class: Protein Kinase; Tyrosine protein kinase Trk family; TK protein kinase group; Enzyme; Kinase
Chemical probes: AZD1332 (high quality), D2202-1 (high quality), GNF-5837 (high quality), GW 441756, PD081378, PD081813, PD082490, PD082710, PD083787, PD084772, larotrectinib (high quality)
Safety:
Unwanted effects reported when the protein is acted on. In parentheses: how it was acted on, where the effect was seen, and who reports it.
Anxiety (activation; central nervous system; source: Brennan et al. (2024))
ataxia (inhibition; central nervous system; source: Brennan et al. (2024))
Cognitive disorder (inhibition; central nervous system; source: Brennan et al. (2024))
dizziness (inhibition; central nervous system; source: Brennan et al. (2024))
dysgeusia (inhibition; source: Brennan et al. (2024))
epilepsy (activation; central nervous system; source: Brennan et al. (2024))
grey matter heterotopia (activation; central nervous system; source: Brennan et al. (2024))
myalgia (inhibition; muscle; source: Brennan et al. (2024))
orthostatic hypotension (inhibition; cardiovascular; source: Brennan et al. (2024))
peripheral sensory neuropathy (inhibition; source: Brennan et al. (2024))
seizures (activation; central nervous system; source: Brennan et al. (2024))
weight gain (inhibition; source: Brennan et al. (2024))
weight loss (inhibition; source: Brennan et al. (2024))
require glucarpidase treatment (source: ClinPGx)
Gene: Protein-coding gene on chromosome 1 (156,815,636 to 156,881,850, forward strand). Ensembl gene ENSG00000198400.
Subcellular location: Cell membrane; Early endosome membrane; Late endosome membrane; Recycling endosome membrane
Subcellular location (Human Protein Atlas): Cytosol; Vesicles
Pathways (Reactome):
Signal Transduction: ARMS-mediated activation; Frs2-mediated activation; NGF-independant TRKA activation; PI3K/AKT activation; PLC-gamma1 signalling; Retrograde neurotrophin signalling; Signalling to RAS; Signalling to STAT3; Signalling to p38 via RIT and RIN; TRKA activation by NGF
Gene Ontology:
Molecular function: identical protein binding; nerve growth factor binding; nerve growth factor receptor activity; protein binding; protein homodimerization activity; protein tyrosine kinase activity; transmembrane receptor protein tyrosine kinase activity; neurotrophin binding; neurotrophin receptor activity; ATP binding; GPI-linked ephrin receptor activity; kinase binding; neurotrophin p75 receptor binding; protein kinase activity
Biological process: cellular response to amyloid-beta; cellular response to nerve growth factor stimulus; negative regulation of cell population proliferation; nerve growth factor signaling pathway; neurotrophin TRK receptor signaling pathway; peptidyl-tyrosine autophosphorylation; peptidyl-tyrosine phosphorylation; positive regulation of ERK1 and ERK2 cascade; positive regulation of GTPase activity; positive regulation of neuron projection development; positive regulation of Ras protein signal transduction; protein autophosphorylation; protein phosphorylation; axonogenesis involved in innervation; cell surface receptor protein tyrosine kinase signaling pathway; negative regulation of apoptotic process; negative regulation of neuron apoptotic process; positive regulation of phosphatidylinositol 3-kinase/protein kinase B signal transduction; positive regulation of programmed cell death; programmed cell death involved in cell development; sympathetic nervous system development; axon guidance; cellular response to nicotine; circadian rhythm; detection of mechanical stimulus involved in sensory perception of pain; and 14 more
Cellular component: plasma membrane; receptor complex; axon; early endosome; early endosome membrane; endosome membrane; late endosome; late endosome membrane; protein-containing complex; recycling endosome membrane; cell surface; cytoplasm; dendrite; endosome; membrane; mitochondrion; neuronal cell body; recycling endosome
Genetic constraint (gnomAD): Loss-of-function variants: 62 observed, 80.3 expected, observed/expected ratio (o/e) 0.77, 90% interval 0.63 to 0.95. The upper end of that interval is the gene's LOEUF score, 0.95, which puts it in group 4 of 6, group 1 being the genes least tolerant of losing a copy. Missense variants: 967 observed, 1,048.2 expected, observed/expected ratio (o/e) 0.92, 90% interval 0.87 to 0.97. Synonymous variants: 469 observed, 436.88 expected, observed/expected ratio (o/e) 1.07, 90% interval 1 to 1.16.
Gene-disease validity (ClinGen):
ClinGen rates the evidence that NTRK1 causes each of these diseases.
hereditary sensory and autonomic neuropathy type 4 (autosomal recessive): Definitive. Hereditary sensory and autonomic neuropathy, type 4 (HSAN4) is an inherited disorder characterized by anhidrosis, insensitivity to pain, self-mutilating behavior and episodes of fever.
Cancer hallmarks: invasion and metastasis (promotes); suppression of growth (promotes); angiogenesis (promotes); genome instability and mutations (suppresses); tumour promoting inflammation (suppresses); escaping programmed cell death (suppresses); proliferative signalling (promotes); angiogenesis (suppresses); escaping immune response to cancer; escaping programmed cell death (promotes)
Homologues: Orthologues: chimpanzee NTRK1 (99% identical), macaque NTRK1 (98% identical), dog NTRK1 (92% identical), pig NTRK1 (92% identical), rabbit NTRK1 (91% identical), guinea pig NTRK1 (87% identical), mouse Ntrk1 (87% identical), rat Ntrk1 (86% identical), tropical clawed frog ntrk1 (58% identical), zebrafish ntrk1 (52% identical). Paralogues in human: NTRK3 (51% identical), NTRK2 (49% identical), MUSK (28% identical), ROS1 (26% identical), IGF1R (25% identical), INSRR (25% identical), ROR1 (25% identical), ROR2 (25% identical), INSR (24% identical), ALK (22% identical), AXL (21% identical), MET (21% identical), and 41 more.
Diseases named in the same sentence as NTRK1 in open-access papers:
NTRK1 is named in the same sentence as 430 diseases in open-access papers, as found by Europe PMC text mining. Sharing a sentence is not in itself a finding about the gene and the disease. The quoted sentences say what the papers report.
neuroblastoma (135 papers, 1996 to 2026). Neuroblastoma (NB) is the most common solid, extracranial childhood tumor. "Alternative oncogenic mechanisms include TrkA alternative splicing, implicated in neuroblastoma, and in-frame deletion of NTRK1, related to acute myeloid leukemia." (PMID 35743191, 2022). "Amongst these genes were neuroblastoma-associated genes NTRK1, BCL11A, TH and CHGB, as well as HMX1, a transcription factor on chromosome 4 that is a master regulator of neural crest development." (PMID 36071103, 2022). "High expression of the receptor tyrosine kinase TrkA/NTRK1 is associated with a favorable outcome in several solid tumors of childhood including neuroblastoma." (PMID 34885133, 2021). "Transcriptional profiling revealed that the major antagonistic programs driving gene expression in neuroblastoma are linked to either NTRK1 or MYCN expression." (PMID 34771457, 2021). "Expression of TrkA/NTRK1 has also been linked to heterotypic cell interactions enabling neuroblastoma cells to communicate with immune cells and stromal cells." (PMID 34885133, 2021). "Activating splice variants of NTRK1 have been described in neuroblastoma and have been recognised as having oncogenic capacity." (PMID 33620682, 2021). "In summary, to the best of our knowledge this is the first report causally linking TrkA/NTRK1 activation and regulation of the G2-checkpoint in neuroblastoma cells." (PMID 34885133, 2021). "In neuroblastoma, NTRK1 expression is associated with benign clinical features (e.g., young age, favorable pathology and non-MYCN amplified genetic status), tumor cell differentiation and good outcome." (PMID 29947893, 2018). "We further investigated the biological mechanisms underlying the postulated interactions between neuroblastoma and stromal cells using neuroblastoma cell lines with stable or inducible NTRK1 expression and primary Schwann cell cultures." (PMID 25361003, 2014). "Also, the mechanisms underlying the enhancement of the immune response by NTRK1 and the connection between the immune response and spontaneous regression remain to be identified in stage 4S neuroblastoma." (PMID 41189817, 2025). "Furthermore, this signature has potential to be a target for treatment and a strong indicator of gene expression changes underlying NGF independent NTRK1 activation promoting differentiation of neuroblastoma cells." (PMID 38398114, 2024). "During development, TrkA/NTRK1 governs migration and differentiation of neuronal precursor cells, while it is associated with mitotic dysfunction and altered DNA damage response, among others, in neuroblastoma." (PMID 34885133, 2021). "Selection of multiple exons for a single gene could imply differential exon usage, which has already been proven for NTRK1 expression in neuroblastoma: NTRK1 isoforms have been reported to be associated with different patient outcome." (PMID 25295525, 2014). "In neuroblastoma, the most common solid tumor of childhood, excellent prognosis is associated with extensive Schwann cell (SC) content and high-level expression of the neurotrophin receptor, NTRK1/TrkA, which is known to mediate neuroblastoma cell differentiation." (PMID 25361003, 2014). "Schwann cells then secrete NGF that promotes the differentiation of neuroblastoma cells with NTRK1 expression." (PMID 41189817, 2025). "The expression of EPAS1 is significantly positively correlated with the expression of some genes, including NTRK1, which are involved in neuronal differentiation, in neuroblastoma." (PMID 41189817, 2025).
neuroblastoma (continued). "The expression of NTRK1 in neuroblastoma cells stimulates the proliferation and migration of Schwann cells by inducing the secretion of neuregulin 1 (NRG1)." (PMID 41189817, 2025). "High NTRK1 expression is detected in favourable neuroblastomas that spontaneously regress or differentiate." (PMID 38398114, 2024). "We next focused on 1p-intact neuroblastomas and studied the mutational spectrum of neuroblastoma candidate genes (particularly chromosome 1 genes CASZ1, CHD5, PTPN14, KIF1Bβ, NTRK1, and TP73), and their association with clinical prognostic variables." (PMID 35768791, 2022). "The screening results of RF showed that EPS8L1, PLCD4, CHD5, NTRK1, and SLC22A4 were the feature differentially expressed genes (DEGs) of high-risk neuroblastoma." (PMID 35911385, 2022). "The screening results of the RF classifier showed that EPS8L1, PLCD4, CHD5, NTRK1, and SLC22A4 were the most characteristic DEG genes among high-risk neuroblastoma-related genes." (PMID 35911385, 2022). "In the present study, we used four neuroblastoma cell lines with inducible NTRK1 expression to study dynamics in NTRK1 downstream signaling induced by NGF treatment." (PMID 34771457, 2021). "Still, the interaction between features of aggressive neuroblastoma that downregulate NTRK1 signaling is less well understood." (PMID 34771457, 2021). "First, inhibition of TrkA/NTRK1 abrogated the mitotic entry of neuroblastoma cells with activated TrkA/NTRK1." (PMID 34885133, 2021). "It will be interesting to study the function of Lamin A/C to further disentangle MYCN and NTRK1-regulated circuits, which are at the crossroads between proliferation and differentiation in neuroblastoma cells." (PMID 34771457, 2021). "Using fluorescence microscopy, we demonstrated that NGF-induced NTRK1 signaling induces the accumulation of LMNA inside nuclear foci in all neuroblastoma cell lines that were analyzed." (PMID 34771457, 2021). "Here, we report that human neuroblastoma cell lines engineered to express TrkA/NTRK1 in tightly controlled systems fail to activate the G2/M cell cycle checkpoint upon irradiation, which recapitulates the effects of ATM or ATR inhibition." (PMID 34885133, 2021). "Taken together, different layers of evidence suggested a less stringent, dose-independent G2-checkpoint upon irradiation induced by TrkA/NTRK1 activation in neuroblastoma cells in vitro." (PMID 34885133, 2021). "Uncovering the differential phosphorylation of LMNA and STMN1 upon NTRK1 activation gives new clues on NTRK1-mediated regulation of the differentiation and proliferation of neuroblastoma cells." (PMID 34771457, 2021). "Here, we used human neuroblastoma cell lines with inducible TrkA/NTRK1 expression to mechanistically explore the role of TrkA/NTRK1 signaling in checkpoint activation after DNA damage induced by ionizing radiation (IR)." (PMID 34885133, 2021). "Both NTRK1 activation in neuroblastoma cells and the induction of LMNA have been independently linked to differentiation." (PMID 34771457, 2021). "For this purpose, we used four neuroblastoma cell lines with inducible NTRK1 expression and activation, two of which were harboring MYCN amplification (IMR5, NGP), while the other two had normal MYCN copy numbers (SH-SY5Y, SKNAS)." (PMID 34771457, 2021). "Here, we obtained the proteomic profiles of an MYCN-amplified neuroblastoma cell line upon ectopic NTRK1 expression and activation." (PMID 34771457, 2021). "Specifically, TrkA (NTRK1) and C (NTRK3) expression are associated with favorable outcomes in neuroblastoma, while TrkB (NTRK2) is associated with biologically aggressive disease." (PMID 29207623, 2017). "As to the neuroblastoma gene network, the degrees of NTRK1 and CDH19 were much larger than those of other genes." (PMID 27349736, 2016).